PRL (prolactin)
Diseases named in the same sentence as PRL in open-access papers (continued):
Sharing a sentence is not in itself a finding about the gene and the disease.
adenoma (continued). "Most of their adenomas were nonfunctioning or prolactin secreting adenomas, accounting for 49% (31 cases) and 38% (24 cases) of the cohort respectively." (PMID 32546762, 2020). "Compared to non-tumoral pituitary, EPHA4 was 51.5, 5.25, and 3.03 times more up-regulated in ACTH-secreting tumors, TSH, PRL and GH-secreting adenomas and non-functioning adenomas, respectively (p = 0.0001)." (PMID 33168897, 2020). "The third cluster consisted of all the clinically manifest GH, PRL and TSH adenomas." (PMID 33168897, 2020). "Patients who relapsed were not different from those in long-term remission with regard to PRL levels at diagnosis, treatment duration (p = 0.074), cumulative CBG dose (p = 0.223), previous use of other dopamine agonists, and frequency of adenoma disappearance before withdrawal." (PMID 31001736, 2019). "Postoperative pathological examination revealed four cases of non-functioning adenomas, three case of PRL-secreting adenoma, three cases of growth hormone-secreting PAs." (PMID 30506234, 2019). "A subset of genes are hypermethylated in nonfunctional adenomas as well as growth hormone (GH) and prolactin (PRL) secreting adenomas." (PMID 31139150, 2019). "In adults, most PAs are prolactin (PRL)-secreting, while non-functioning adenomas represent the second most common type." (PMID 31877737, 2019). "The presenting pituitary tumors are more commonly PRL- or GH-secreting or non-functioning adenomas, but they are thought to be more aggressive in presentation and more likely to be resistant to standard therapy." (PMID 31877737, 2019). "Immunohistochemistry confirmed exclusive production of GH by the adenomas in all patients, and none of the patients had increased serum prolactin." (PMID 31365626, 2019). "Postoperative pathological examination revealed five cases of non-functioning adenomas, three case of PRL-secreting adenoma, two cases of growth hormone-secreting PAs." (PMID 30506234, 2019). "Sixteen patients had non-secreting adenomas, and 11 secreting adenomas (3 GH, 7 prolactin, and 1 ACTH secreting tumors)." (PMID 29967671, 2018). "Regardless of histological adenoma type, PRL levels decreased at postoperative day 1 and remained low thereafter." (PMID 29108291, 2017). "In non-functioning adenomas as well as in PRL-secreting adenomas the expression of Bcl-2 found decreased and BAX protein was increased when associated with pituitary tumor progression." (PMID 29104246, 2017). "Somatotropinomas, with or without prolactin co-secretion, represent the most common AIP mutation positive adenoma type followed by prolactinomas." (PMID 28161730, 2017). "A few clinically non-functioning adenomas have also been described but these usually show positive immunostaining for GH and prolactin." (PMID 28161730, 2017). "A study previously published by the authors showed that c-erbB2 was expressed in 79% of aggressive nonfunctioning adenomas and in 52% of GH or prolactin secreting adenomas." (PMID 27635138, 2016). "Comparison of functioning (GH and PRL expressing, n = 28) and non-functioning (null cell and silent gonadotroph, n = 20) adenomas revealed significantly higher mRNA levels in the functioning tumors (p = 0.023)." (PMID 27655724, 2016). "Nevertheless, as has been previously shown, normal testosterone levels do not exclude the presence of PRL-secreting adenoma." (PMID 28702224, 2015). "Histological examination showed GH expression in four GH producing adenoma, PRL expression in one PRL producing adenoma, and no expression of all pituitary hormones in 22 nonfunctioning adenoma." (PMID 26339240, 2015). "This case highlights that GH and prolactin level elevation is not always from co-secretion by the same adenoma." (PMID 25298881, 2014). "The results demonstrate the importance of vessel diameter and perimeter as biomarkers of different histotypes; PRL-secreting adenomas had larger vessel diameter and perimeter than nonfunctioning and GH-secreting adenomas." (PMID 25431591, 2014).
adenoma (continued). "In macroadenomas, PRL-secreting adenomas had larger vessel diameter and perimeter than nonfunctioning and GH-secreting adenomas." (PMID 25431591, 2014). "As for GH-secreting (n=5) or PRL-secreting adenomas (n=4), the Jagged1 expression levels were not significantly different from those in normal tissue (P=0.786 and P=0.052, respectively)." (PMID 23426998, 2013). "When compared with each other, the diversity of Ki-67 LI in the PRL and non-functional adenomas was varied (P<0.01)." (PMID 24179515, 2013). "The Ki-67 LI level between the PRL and gonadotropic adenomas (P<0.05), the non-functional and GH adenomas (P<0.05) and the non-functional and plurihormonal adenomas (P<0.05) differed from each other significantly." (PMID 24179515, 2013). "Previous studies have demonstrated that Dll1, a potential ligand of Notch3, was strongly downregulated in non-functional tumors and in PRL-secreting adenomas." (PMID 23426998, 2013). "Based on this retrospective study, the mean long-term HRQoL profile of patients with surgically treated NF adenoma seems to be comparable to that of an age-standardized reference population, while patients treated for ACTH- and PRL-secreting PAs seem to have significant HRQoL-impairments." (PMID 23346413, 2012). "DAs have been reported to be more effective in adenomas that co-secrete prolactin (PRL), which express more D2 receptors, but this has not been universally confirmed." (PMID 22550484, 2012). "Like adenomas, the vast majority of reported pituitary carcinomas are endocrinologically active (88%), with most secreting adrenocorticotrophic hormone (ACTH) or prolactin (PRL)." (PMID 19356251, 2009). "Elevated prolactin was the most common hormonal laboratory abnormality (n = 16, 43%), with 10 (63%) of these patients being diagnosed with a prolactinoma, 4 (25%) nonfunctioning adenomas, 1 cyst, and 1 indeterminate lesion." (PMID 40321172, 2025). "However, the potential impact of gender differences in prolactin levels on estimating adenoma size (micro- vs. macroadenoma) is not yet fully comprehended." (PMID 38544490, 2024). "Meanwhile, depending on the tumor characteristics (tumor size or cavernous sinus invasion), the surgical goal for PRL-secreting adenomas may be maximal cytoreduction rather than aggressive GTR, which may also affect the surgical cure rate." (PMID 37025271, 2023). "It is questionable whether it was a non-functioning adenoma with pituitary stalk compression and with decreased negative regulation of prolactin and compression of the rest of the hormonal axis." (PMID 37908013, 2023). "Histochemical staining for PRL + GH + ACTH was most commonly performed, and this method was used to diagnose 14 patients (n = 3, microadenoma; n = 5, large adenoma; n = 6, unknown; and n = 2, intraoperative and postoperative diagnoses of invasive pituitary tumor)." (PMID 35284477, 2022). "These idiopathic cases had mild elevations of PRL and, importantly, all of them had a marked response (i.e., > 300% from baseline PRL) to the metoclopramide test, thus not in favor of picoprolactinomas (i.e., maximal size of adenoma < 3 mm, usually not visualized on pituitary MRI)." (PMID 35250884, 2022). "While Pit1 lineages including cells expressing GH and PRL, as well as SF1 lineages expressing FSH and LH, were detected in the hPITO37N and hPITO38N organoid cultures, these cell populations were significantly reduced within the patient’s matched adenoma tissue." (PMID 36359740, 2022). "The IHC subtypes of PAs are composed of growth hormone (GH), prolactin (PRL), adrenocorticotropic hormone (ACTH), thyroid-stimulating hormone (TSH), and follicle-stimulating hormone-luteinising hormone (FSH-LH), including the monohormonal and plurihormonal adenomas." (PMID 35069413, 2021). "Interestingly, none of the adenomas examined in this study demonstrated a transition from hyperplasia to adenoma or showed any tumor cells with GH and PRL co-localization." (PMID 27245663, 2016).
adenoma (continued). "Interestingly, DR2 expression levels in somatotrophs are correlated with dopamine agonist response rates both in vitro and in vivo, and analysis of prolactin and DR2 expression patterns within GH-secreting adenomas has been proposed as a guide for pharmacotherapy strategies in acromegaly patients." (PMID 27517036, 2016). "Previous studies demonstrated that medical therapy has good effect in the treatment of PRL secreting adenomas, the patients with drug treatment had normal menstrual cycle and got pregnant, and thus medical therapy can be used as the preferred treatment for PRL secreting adenomas." (PMID 25270611, 2015). "The differences in vessel architecture in different histotypes, particularly larger vessel diameter and perimeter in PRL-secreting adenomas than nonfunctioning and GH-secreting adenomas, suggest the hormonal regulation of vessel architecture other than angiogenesis." (PMID 25431591, 2014). "Our proteome was from the pure prolactin cells of prolactinomas by immuno-LCM while the other proteome by Xianquan Zhan was from the whole non-functional adenoma tissues, which may be the main reason for the difference." (PMID 20205839, 2010). "Raised prolactin levels occur due to either a prolactin-secreting adenoma within the pituitary or from the lack of dopamine-mediated suppression from stalk dysfunction, which can occur if the stalk is distorted by intra- or extra-sella lesions, as we believe was the case in this patient." (PMID 18638386, 2008). "Histological subtypes included 9 prolactin-secreting adenomas (10.71%), 9 growth hormone–secreting adenomas (10.71%), 5 ACTH adenomas (4.76%), and 61 non-functioning adenomas (72.62%)." (PMID 41480352, 2025). "Some subsequent studies reported that non-functional adenomas can secrete LH, FSH, and PRL in cell culture in vitro." (PMID 35284477, 2022). "CACNA2D4 expression was significantly more up-regulated in non-functioning adenomas (367.03) than in ACTH-secreting adenomas (1.659) or TSH-, GH- and PRL-secreting tumors (0.797) (p = 0.0089)." (PMID 33168897, 2020). "Another large retrospective analysis compared 75 SCAs and 1726 adenomas with negative immunostaining for ACTH, PRL, and GH (LH/FSH staining was not reported)." (PMID 30020466, 2019). "Transgenic overexpression of the pituitary stem cell marker PROP1 under control of the αGSU promoter also leads (after 1 year) to pituitary tumors including non-hormonal, GH-, PRL-, GH/PRL-, PRL/αGSU-, and TSH-producing adenomas." (PMID 29255445, 2017). "In all 71 cases, there were 14 growth hormone (GH), 13 prolactin (PRL), five adrenocorticotropic hormone (ACTH), seven gonadotropic, 10 non-functional and 22 plurihormonal adenomas." (PMID 24179515, 2013). "In cases with increasing prolactin levels (not yet reaching the ULN), radiological recurrence (ie, reappearance of an adenoma on conventional MRI after initial radiological remission) may provide an additional argument for the presence of active disease." (PMID 41017446, 2026). "There were five null cell adenomas that were stained negative for all transcription factors which also exhibited weak and focal hormone IHC staining (three ACTH only, one ACTH with concomitant prolactin and one prolactin only)." (PMID 38756997, 2024). "Notably, WHO suggested that growth hormone-prolactin (GH-PRL) and follicle-stimulating hormone-luteinizing hormone (FSH-LH) adenomas are not PPA." (PMID 38260014, 2023).
adenoma (continued). "Although gonadotroph adenoma is the most common subtype among non-functional adenomas, some cases with thyroid stimulating hormone (TSH), growth hormone (GH), adrenocorticotropic hormone (ACTH), or prolactin (PRL) stainings behave as silent adenomas with no secretion." (PMID 31100921, 2019). "These pituitary tumours may secrete hormones such as prolactin, GH, ACTH, FSH, LH and TSH, or they may be non-secreting, which is also referred to as non-functioning adenomas." (PMID 26320859, 2016). "Preoperative hormonal assessments showed that prolactin (PRL) and follicle-stimulating hormone (FSH) were above the upper limit of their reference intervals; however, no overt related clinical symptoms existed, and the tumor behaved as a “clinically non-functioning” adenoma." (PMID 40843886, 2025). "In this group of women, PRL at diagnosis and before withdrawal, treatment duration, cumulative CBG dose, previous use of other dopamine agonists, and frequency of adenoma disappearance before withdrawal were not different whether patients relapsed or remained in long term remission (data not shown)." (PMID 31001736, 2019).
Infertility (193 papers, 2005 to 2026). "Elevated circulating serotonin has been associated with male infertility, and serotonin can increase prolactin and cortisol via multiple mechanisms; heightened levels of these hormones have been implicated in menstrual irregularities and infertility." (PMID 41304935, 2025). "A p-value of <0.05 (p = 0.001) showed a statistically significant association between infertility type and prolactin levels, with primary infertility showing a higher prevalence of raised prolactin compared to secondary infertility." (PMID 40535391, 2025). "Our study shows that the high occurrence of anemia and increased prolactin levels in women of reproductive age suggest their contributory role in causing infertility." (PMID 40535391, 2025). "The authors of the recent review, who focused on the connection of prolactin and uterine pathology, stated that prolactin is “clearly implicated in endometriosis-associated infertility”." (PMID 39407928, 2024). "Prolactin (PRL)-secreting tumours are associated with infertility and can be reverted by dopamine agonist (DA) therapy." (PMID 38499816, 2024). "Studies have shown that a higher ratio of serum cortisol to follicular cortisol was associated with pregnancy, and that infertile women had higher levels of stress in terms of circulating prolactin and cortisol compared to fertile women in the control group." (PMID 36733805, 2022). "Marijuana use is associated with hormonal imbalance in a cohort of infertile men, significantly lowering E2 serum levels while increasing prolactin serum concentrations." (PMID 36303626, 2022). "Females seek medical advice earlier due to prolactin causing inhibition of gonadotropins leading to menstrual irregularities, galactorrhea, and infertility." (PMID 36337795, 2022). "The aim of the current study was to evaluate the causes of Hyper-PRL in infertile women referred to the Yazd Infertility Center." (PMID 35098010, 2021). "The mean prolactin level, age, and duration of infertility are presented in table I. The frequency of Hyper-PRL causes is presented in table II." (PMID 35098010, 2021). "Our study aimed to investigate if serum prolactin (PRL) levels associated with insulin resistance and beta-cell dysfunction in infertile patients with polycystic ovary syndrome (PCOS)." (PMID 33716958, 2021). "On the contrary, all known adverse effects of PRL result from its overproduction, which can cause infertility in women, impotence in men, and aggravation of autoimmune diseases." (PMID 34071395, 2021). "Low serum PRL levels within the normal range associates with a higher incidence of insulin resistance and beta-cell dysfunction in infertile women with PCOS." (PMID 33716958, 2021). "As generally known, abnormal increase of PRL levels in the blood cause menstrual cycle disorders, anovulation, luteal phase deficiency, infertility, RPL, worsening the pregnancy outcomes." (PMID 33426414, 2020). "Women with unexplained causes of infertility showed positive association between WC, WHtR and prolactin levels, which suggest possible obesity-induce hyperprolactinemia and poor fertility outcomes." (PMID 31455408, 2019). "The present study aimed to determine the frequency of endometriosis and association of prolactin with endometriosis in infertile women." (PMID 26000006, 2015). "In particular, prolactinomas are associated with elevated levels of the hormone prolactin, which might lead to menstrual dysfunction and infertility issues in women." (PMID 41003488, 2025). "Because endometriosis and elevated prolactin levels are independently associated with infertility early hypotheses proposed that hyperprolactinemia might contribute directly to infertility in women with endometriosis." (PMID 41463090, 2025). "Interestingly, while long-term vortioxetine decreased prolactin, infertility was more closely associated with corticosterone elevation rather than prolactin suppression." (PMID 41304935, 2025).